BRCA2 (BRCA2 DNA repair associated)
Diseases named in the same sentence as BRCA2 in open-access papers (continued):
Sharing a sentence is not in itself a finding about the gene and the disease.
breast cancer (continued). "The results showed an association between the 86-SNV PRS and breast cancer risk for each of the carrier populations: BRCA1 (OR 1.20; 95% CI 1.10–1.32), BRCA2 (OR 1.23; 95% CI 1.12–1.34), ATM (OR 1.37; 95% CI 1.21–1.55), and PALB2 (OR 1.34; 95% CI 1.16–1.55)." (PMID 39858629, 2025). "In men, several factors significantly increase the risk of breast cancer, including BRCA2 and BRCA1 mutations, advanced age, Klinefelter syndrome, elevated estrogen levels, radiation exposure, and a family history of breast cancer." (PMID 40800071, 2025). "These rates are intermediate between those reported in BRCA1 carriers (57% high grade, 85% TN) and BRCA2 carriers (56% high grade, 23% TN), suggesting differences in tumor biology between PHTS and BRCA-associated breast cancers." (PMID 40075703, 2025). "It has been reported that patients with pancreatic cancer carry rare germline deleterious variants of breast cancer susceptibility genes such as BRCA1, BRCA2, PALB2, and ATM." (PMID 38204267, 2025). "Poly (ADP-ribose) polymerase (PARP) inhibitors have emerged as a promising therapeutic strategy in the treatment of breast cancer, particularly for patients with hereditary BRCA1 and BRCA2 mutations." (PMID 40141415, 2025). "Mutation carriers face a cumulative breast cancer risk by age 70 of approximately 65% for BRCA1 and 45% for BRCA2." (PMID 40075637, 2025). "For breast cancer, there were 6 genes with a posterior probability > 0.9: BRCA2, BRCA1, PALB2, CHEK2, ATM, and MAP3K1." (PMID 40073867, 2025). "Over 64% of NPCs are deficient in a pathway that depends on the breast cancer susceptibility genes BRCA1 and BRCA2, which accurately repair DNA crosslinks and breaks via the homologous recombination pathway." (PMID 39885374, 2025). "It was previously reported in a Spanish family with non-BRCA1/BRCA2 early breast/ovarian cancer family history and the incidence of pancreatic cancer, as well as in a patient with unilateral breast cancer from the WECARE study." (PMID 40040726, 2025). "In comparison, 76% of BRCA2/PALB2 carriers with T1N0 breast cancer had ER + HER2- disease, only half of whom received chemotherapy (eTable 1)." (PMID 40275390, 2025). "Family history plays a critical role in breast cancer risk, as germline mutations in the tumor suppressor genes BRCA1 and BRCA2 are strongly associated with an inherited predisposition to the disease." (PMID 39997609, 2025). "On the other hand, the Breast Cancer Association Consortium studied 4187 women with DCIS and identified a mutation of BRCA1 in 0.24% and of BRCA2 in 0.66% of cases." (PMID 40002208, 2025). "This study describes the frequency and type of variants in hereditary cancer genes associated with breast cancer detected by the next-generation sequencing of a panel of 111 hereditary cancer genes, including BRCA1 and BRCA2." (PMID 40259910, 2025). "Equol prompted the promoter hypomethylation of tumor suppressor genes BRCA1 and BRCA2 in breast cancer cells." (PMID 40650308, 2025). "Genetic testing for commonly occurring oncogenes associated with breast cancer—specifically BRCA1 and BRCA2—is progressively becoming a standard procedure in numerous African countries for patients diagnosed with breast cancer." (PMID 40313245, 2025). "GNPDA1 and SLC25A16 play important roles in the BRCA1, BRCA2, and pro-oncogenic actions of the androgen receptor in breast cancer development." (PMID 40278313, 2025).
breast cancer (continued). "Also, there are particular P/LP variants in moderate penetration genes that confer similar risks of BC as high-risk genes, for instance, the missense pathogenic variant c.7271T>G in ATM may considerably increase the risk of breast cancer in a similar proportion as P/LP variants in BRCA2." (PMID 40508121, 2025). "In most breast cancer susceptibility genes, Polish common founder mutations are present, including BRCA1, BRCA2, PALB2, and CHEK2, which constitute the majority (>80%) of all mutations detected in these genes in Polish women with breast cancer." (PMID 40649769, 2025). "This survey indicates that the tumors occurring in women with PJS seem to be slower growing, less likely to recur, and have better prognosis than tumors that are reported in other high-risk breast cancer groups, like BRCA1 and BRCA2 PV carriers." (PMID 40317347, 2025). "This study presents a multi-omics analysis of acquired Olaparib resistance in BRCA1- and BRCA2-mutant breast cancer cell lines." (PMID 40669753, 2025). "Only one study assessed the prevalence of BRCA2 methylation in sporadic breast cancers (all molecular subtypes) showing a prevalence of 12.5%." (PMID 39392573, 2025). "Of these, one individual was found to carry a variant in BRCA2 (NM_000059.3), and another one carried a variant in PALB2 (NM_024675.3); both genes being associated with increased risk for breast cancer." (PMID 40679974, 2025). "Breast cancer (BC) is the most common cancer affecting women, with up to 10% of cases attributed to hereditary gene predispositions, such as BRCA1 and BRCA2 mutations." (PMID 40422528, 2025). "BRCA1 and BRCA2 genes are the most well-known and well described predictors of hereditary breast cancer due to their clinical importance." (PMID 40531958, 2025). "In breast cancer, particularly TNBC, HRD predicts responsiveness to platinum agents and PARPi like talazoparib, especially in BRCA1/BRCA2-mutated cases." (PMID 40864792, 2025). "Internal validity of the model was established through the convergence on BRCA2 as a breast cancer hotspot." (PMID 39838298, 2025). "A genetic predisposition to breast cancer is linked to the BRCA1 and BRCA2 genes, with an ongoing danger of 40–60% in BRCA1 mutation carriers and 13–30% in BRCA2 alterations carriers." (PMID 40141415, 2025). "The cumulative lifetime risk of breast cancer is estimated at 72% (95% confidence interval [CI], 65%–79%) for BRCA1 carriers and 69% (95% CI, 61%–77%) for BRCA2 carriers by the age of 80." (PMID 41083355, 2025). "It is also noteworthy that the low frequency of BARD1 PVs (less than 1%) in HBOC patients contrasts sharply with the much higher frequencies of BRCA1 and BRCA2 PVs, reinforcing the view of BARD1 as a gene conferring a moderate to low risk for breast cancer." (PMID 41301857, 2025). "Prior to the progression to breast cancer, the expression of the HLA-DQB1 gene in BRCA2-mutated breast cells has been identified to be significantly upregulated, which is correlated with MHC class II and plays a critical role in antigen presentation." (PMID 40830526, 2025). "HRD is a pivotal biomarker in oncology, particularly for ovarian and breast cancers, expanding actionable therapeutic targets beyond BRCA1/BRCA2 mutations to enhance patient stratification for PARPi and platinum-based therapies." (PMID 40864792, 2025). "This systematic review aims to broaden the discussion of BRCA1 and BRCA2 beyond mammary tumors, exploring their implications in various canine cancers." (PMID 40004231, 2025). "Eight different genes, including ATM, BRCA1, BRCA2, CHEK2, PALB2 (FANCN), RAD51C, and RAD51D, demonstrate significant correlations with an increased risk of breast cancer when harboring pathogenic variations." (PMID 40800071, 2025).
breast cancer (continued). "Many genetic variants only cause a slight increase in radiation sensitivity such as heterozygous pathogenic variants in the breast cancer risk genes BRCA1 and BRCA2." (PMID 41210219, 2025). "Of the 143 patients, 24 (16.8%) had a PGV in a breast cancer susceptibility gene (BRCA1, n = 17; BRCA2, n = 5; PALB2, n = 1; CHEK2, n = 1)." (PMID 39964682, 2025). "This review focuses on the management of women at high risk for breast cancer, particularly those with pathogenic variants in BRCA1 and BRCA2, who face elevated lifetime risks." (PMID 41083355, 2025). "Mutations in genes such as BRCA1, BRCA2, and PIK3CA interfere with DNA repair and trigger oncogenic signaling pathways in breast cancer." (PMID 40565055, 2025). "Non-modifiable factors include female sex, older age, a positive family history of breast cancer and the presence of BRCA1 or BRCA2 mutations." (PMID 40940924, 2025). "The BRCA1 and BRCA2 genes, which stand for breast cancer gene 1 and gene 2, produce proteins that aid in the repair of damaged DNA in normal conditions." (PMID 40141415, 2025). "This cohort study evaluates the long-term outcomes of breast-conserving treatment (BCT) on recurrence and survival in patients with breast cancer with BRCA1 and BRCA2 pathogenic variants." (PMID 40366658, 2025). "Based on mutation frequencies and cancer risk, the two most important susceptibility genes for breast cancer are BRCA1 and BRCA2." (PMID 40649769, 2025). "While one-third of breast cancer cases show familial clustering, only 5–10% are due to high-penetrance mutations in genes such as BRCA1 and BRCA2." (PMID 40243654, 2025). "The life-time risk of breast cancer for carriers of BRCA1 and BRCA2 pathogenic variants is about 65% and 45%, respectively." (PMID 40296163, 2025). "The estimated cumulative risks of breast cancer by age 70 in two meta-analyses were 55% to 65% for carriers of BRCA1 pathogenic variants and 45% to 47% for carriers of BRCA2 pathogenic variants." (PMID 39996890, 2025). "Patients with breast cancer with deleterious variants associated with the BRCA1 and BRCA2 genes had a mean age of 43 years (SD = 11.71) and 41 years (SD = 14.62), respectively." (PMID 40259910, 2025). "“Homologous recombination” is the most well-known DDR pathway in breast cancer, particularly in relation to BRCA1 and BRCA2 mutations, which significantly increase the risk of the disease." (PMID 40510149, 2025). "Breast cancer is a multifaceted disease, influenced by various factors, including genetic mutations (e.g. BRCA1, BRCA2), hormonal influences, age, and gender." (PMID 40353126, 2025). "HRD-positive luminal breast cancers with ATM or BRCA1/BRCA2 defects show tumor reduction with PARPi." (PMID 40864792, 2025). "In breast cancer, HER2 positivity is observed in 2.5% and 3.2% of women with BRCA1 or BRCA2 mutations, respectively, compared to 27.7% and 8.2% for triple-negative tumors." (PMID 39985003, 2025). "On the other hand, a somatic nonsense pathogenic variant in BRCA2 (variant allele frequency = 15%) and a two-hit event in APC (VAF = 80%) were also found in her left breast cancer." (PMID 40601170, 2025). "Genes expressed in the surface membrane or extracellular matrix and related to patient outcomes included B3GNT7 and CTSV in BRCA2-mut breast cancers, exhibiting detrimental prognoses." (PMID 40647506, 2025).
breast cancer (continued). "For PALB2 P/LP variant carriers, the surveillance for breast cancer should be equivalent to that for BRCA1 and BRCA2 P/LP variant carriers." (PMID 39858629, 2025). "An estimated 10% of breast cancer cases are due to an underlying hereditary predisposition, such as a pathogenic/likely‐pathogenic variant in BRCA1 or BRCA2." (PMID 39907309, 2025). "Ovarian cancer data enabled an additional test for EBV involvement in breast cancer because, like breast cancer, BRCA1 or BRCA2 mutations can also predispose patients to ovarian cancer." (PMID 39885374, 2025). "Another study indicated that the estimated lifetime breast cancer risk for BRCA1 and BRCA2 PV carriers increased with higher PRS313 scores, though the observed effect was smaller than in the general population or among carriers of PVs in ATM, CHEK2, and PALB2." (PMID 40296163, 2025). "In the case of BRCA2-mut breast cancer, most pathways were also related to the immune system, including cytokine production, inflammasome regulation, interferon response, and T-cell migration, among others." (PMID 40647506, 2025). "A strong association between the risk of breast cancer and family history was found for ATM, BRCA1, BRCA2, CHEK2, and PALB2 P/LP variant carriers." (PMID 39858629, 2025). "Patient, tumor, and treatment characteristics at the time of breast cancer diagnosis in BRCA1 versus BRCA2 carriers according to the timing of germline BRCA testing are reported in the Data Supplement (online only)." (PMID 39993249, 2025). "A retrospective study conducted on a Chinese pan-cancer patient cohort revealed the presence of reversion mutations in three HRR-associated genes: BRCA1, BRCA2, and PALB2, across breast cancer, pancreatic cancer, OC, and lung cancer." (PMID 40166687, 2025). "Polymorphisms in repair genes (BRCA1, BRCA2, CHEK2, XRCC1, XPD) can reduce DNA repair efficiency, leading to genomic instability and increased breast cancer risk." (PMID 40507526, 2025). "Approximately 3% of breast cancers (approximately 7,500 women per year) result from inherited mutations in the BRCA1 and BRCA2 genes." (PMID 40303990, 2025). "Although male breast cancer accounts for only 1% of all breast cancer cases, it has been linked to HBOC, particularly the BRCA1 and BRCA2 mutations." (PMID 40918841, 2025). "For instance, in South Africa, genetic testing for the BRCA1 and BRCA2 genes in breast cancer has been implemented at the primary healthcare level for over two decades, with plans to upscale to a multigene next-generation sequencing (NGS) panel." (PMID 40313245, 2025). "The study aims to include women carrying a germline P/LP variant (BRCA1, BRCA2, or PALB2), or >5% Tyrer–Cuzick breast cancer risk at ten years, or with a previous diagnosis with intraepithelial neoplasia within the last three years." (PMID 39858629, 2025). "Concerns regarding the potential impact of these interventions on breast cancer risk, particularly among high-risk women with a pathogenic variant in the BRCA1 or BRCA2 genes remains an important clinical concern." (PMID 41214587, 2025). "In PTV meta-analyses including FinnGen10, the BRCA2 association was attenuated, but CHEK2 and PALB2 were more strongly associated with breast cancer." (PMID 41044259, 2025). "In our subgroup analysis of 89 T1N0 breast cancers, 56% of BRCA1-associated cases were TNBC compared to only 18% of BRCA2 and PALB2-associated cases." (PMID 40275390, 2025). "HBOC, which is associated with germline mutations in the breast cancer 1 (BRCA1) and breast cancer 2 (BRCA2) genes, is responsible for breast cancers, OC, pancreatic, and prostate cancer." (PMID 40899374, 2025). "Only KTR14, KRT16, CXCL9, and CFD in BRCA1 Ovarian Cancer and TSPAN7 and CDKN2C in BRCA2 ovarian cancers were highly upregulated, and KANK4, MFGE8, LINC00346, and SA100A1 in BRCA1 mutated breast cancer, and MAGEA4 in BRCA2 breast cancers." (PMID 40647506, 2025).
breast cancer (continued). "In preclinical models and patient samples of ovarian and breast cancer, including ascite metastases and in situ carcinomas, reduced DNA damage-induced nuclear RAD51 is positively associated with BRCA1 or BRCA2 gene defects and patient response to PARPi." (PMID 40830526, 2025). "The findings from this study have highlighted the contribution of genetics, specifically BRCA1 and BRCA2 genes in 120 unselected series of Brunei breast cancer population." (PMID 40531958, 2025). "Stratifying the MWS analysis by age at diagnosis of breast cancer, we observed that among carriers of BRCA1 and BRCA2 PTVs, the odds ratio (OR) for breast cancer aged <55 (vs controls) was more than double that of breast cancer aged ≥55." (PMID 41044259, 2025). "A class of medications known as PARP inhibitors (PARPis) is mainly used to treat breast cancers, especially those with BRCA1 and BRCA2 mutations." (PMID 40141415, 2025). "The second most upregulated gene, partner and localizer BRCA2 (PALB2; >3.1-fold), is involved in DNA damage repair, and its mutation is associated with increased risk of male breast cancers." (PMID 41205594, 2025). "This study presents a review of existing data on the impact of genetic modifiers on breast cancer risk among individuals carrying pathogenic variants in the BRCA1 and BRCA2 genes." (PMID 40296163, 2025). "In the remaining PALB2 affected carriers with HR + HER2- breast cancer, higher 21-gene recurrence scores (similar to that of BRCA2 carriers) have been reported, suggesting that tumor biology and chemotherapy response is likely similar between these groups." (PMID 40275390, 2025). "Some studies highlighted the superior performance of breast cancer-specific models in interpreting pathogenicity of variants in BRCA1, BRCA2, and other breast cancer-related genes." (PMID 41263939, 2025). "For example, studies focusing on breast cancer patients and their families estimated the penetrance of BRCA1 and BRCA2 mutations by age 70 to be 65–85% and 70–84%, respectively." (PMID 39858629, 2025). "First, GNPDA1 was strongly associated with “DNA damage_ATM activation by DNA damage (p = 4.282 × 10−06)”, “BRCA1 and BRCA2 in breast cancer (p = 6.950 × 10−04)”, and “DNA damage_ATM/ATR regulation of G2/M checkpoint: nuclear signaling (p = 8.093 × 10−04)”." (PMID 40278313, 2025). "A comprehensive overview of the distribution of the BRCA2 Met1915Thr genotypes is provided, categorised according to the status of breast cancer patients and healthy controls." (PMID 40843725, 2025). "The Multiplex Taqman assay for the rs80359550 (BRCA2) and rs180177102 (PALB2) variants has shown a strong correlation with breast cancer risk." (PMID 40158114, 2025). "With this in mind, we undertook a systems-level characterization of acquired Olaparib resistance in MDAMB436 and HCC1428 breast cancer cells, which carry BRCA1 and BRCA2 mutations, respectively." (PMID 40669753, 2025). "Protein-truncating variants in established susceptibility genes BRCA2, BRCA1, CHEK2, PALB2, ATM and MAP3K1 were associated with a risk of breast cancer, while BARD1 and ATRIP met exome-wide significance for the first time." (PMID 41044259, 2025). "Specifically, multiple breast cancer clusters in BRCA1 and BRCA2 are associated with relatively higher risks of breast cancer and relatively lower risks of ovarian cancer." (PMID 40007994, 2025). "Previous studies have shown that approximately 5% of breast cancer cases are associated with BRCA1, BRCA2, and other high-penetrance gene mutations." (PMID 40666442, 2025). "While most breast cancer cases are sporadic, about 5–10% are hereditary, often associated with pathogenic variants in the BRCA1 or BRCA2 (BRCA1/2 hereafter) genes." (PMID 40390061, 2025).